FAIM2 (Fas apoptotic inhibitory molecule 2)
Diseases named in the same sentence as FAIM2 in open-access papers (continued):
Sharing a sentence is not in itself a finding about the gene and the disease.
Graves disease (2 papers, 2020 to 2024). Graves' disease is an autoimmune disorder that leads to overactivity of the thyroid gland (hyperthyroidism).It is caused by an abnormal immune system response that causes the thyroid gland to produce too much thyroid hormones. "Genotype and allele frequencies for FAIM2 gene polymorphism (rs7138803) in groups with Graves’ disease (GD) and with Hashimoto’s thyroiditis (HT) compared to control group." (PMID 33193078, 2020). "Notably, a study associated a SNP of FAIM2 with antibody levels in patients with Graves’ disease and Hashimoto’s thyroiditis." (PMID 39337639, 2024). "The aim of the study was to analyze the polymorphisms of the IL-2RA (rs7093069), FAIM2 (rs7138803) and PADI4 (rs1748033) genes and their correlation to thyroid hormones and anti-thyroid antibodies in pediatric patients with Graves’ disease and Hashimoto’s thyroiditis compared to the control group." (PMID 33193078, 2020).
hepatocellular carcinoma (2 papers, 2021). A malignant tumor that arises from hepatocytes. "DCST1-AS1 acts as a ceRNA to regulate expression of FAIM2 through sponging miR-1254 in hepatocellular carcinoma." (PMID 34414241, 2021).
neuroblastoma (2 papers, 2016 to 2021). Neuroblastoma (NB) is the most common solid, extracranial childhood tumor. "Upon validation, FAIM2, which was highly abundant by proteomics specifically in neuroblastoma cells, GD2, CD56, VIM and B7-H3 were selected for multiplex imaging of DTCs." (PMID 34503120, 2021). "A subset of DTCs exhibited a high expression of FAIM2, an inhibitory protein in the Fas-apoptotic pathway, which we included into the 20-plex panel upon data mining of a previously generated neuroblastoma RNA-seq and proteomics dataset." (PMID 34503120, 2021). "Moreover, we revealed novel markers, including FAIM2 (Fas Apoptotic Inhibitory Molecule 2), to better capture heterogeneity of DTCs in bone marrow metastases of neuroblastoma patients." (PMID 34503120, 2021). "Interestingly, in our single-cell analysis of eight neuroblastoma bone marrow samples, FAIM2 was expressed only in a subset of DTCs." (PMID 34503120, 2021). "To test the hypothesis that FAIM2 could act as a novel NE tumor marker, we examined the CCLE database for NE tumor cell lines with FAIM2 expression data, and found 17 neuroblastoma (NB) cell lines." (PMID 27677402, 2016). "In conclusion, we here provide a validated 20-plex MELC panel for neuroblastoma composed of DTC markers, including a novel candidate marker called FAIM2, as well as myeloid, lymphoid, mesenchymal, and hematopoietic stem and progenitor cell markers." (PMID 34503120, 2021). "We show that FAIM2 marks a subset of DTCs and can serve as a complementary biomarker for capturing DTC heterogeneity in neuroblastoma." (PMID 34503120, 2021). "As other markers that were found to be expressed by DTCs, FAIM2 was not exclusive to neuroblastoma cells, but was also found on other cell types in the bone marrow." (PMID 34503120, 2021).
obsessive-compulsive disorder (2 papers, 2024). A disorder characterized by the presence of persistent and recurrent irrational thoughts (obsessions), resulting in marked anxiety and repetitive excessive behaviors (compulsions) as a way to try to decrease that anxiety. "Polymorphisms of FAIM2 are associated with childhood obesity, autoimmune thyroid disease, and obsessive-compulsive disorder." (PMID 39337639, 2024). "Indeed, several mRNAs that were differentially expressed in stressed visual cortices are recognized mediators of brain development and neurodevelopmental disorders, including Deaf1 in memory deficits and anxiety-like behaviours, Faim2 in obsessive compulsive disorder and Hrh3 in schizophrenia." (PMID 39739746, 2024).
pancreatic adenocarcinoma (2 papers, 2022 to 2025). "Disease free survival analysis shows high FAIM2 expression has a better prognosis in cholangio carcinoma (CHOL), LGG, ovarian serous cystadenocarcinoma (OV), pancreatic adenocarcinoma (PAAD), and rectum adenocarcinoma (READ) and has a poor prognosis in KIRC." (PMID 36185230, 2022).
retinal detachment (2 papers, 2012 to 2024). An eye emergency condition which may lead to blindness if left untreated. "We report here that while basal level of interaction between FAIM2 and αA- and αB-crystallin was observed in the attached retina, a significant increase in FAIM2 and αA-crystallin association was detected following retinal detachment." (PMID 39311341, 2024). "Therefore, we attempted to evaluate the role of α-crystallin in photoreceptor survival in an experimental model of retinal detachment, as well as its association with the intrinsically neuroprotective protein Fas-apoptotic inhibitory molecule 2 (FAIM2)." (PMID 39311341, 2024). "On a mechanistic level, we previously reported that photoreceptor apoptosis is accelerated in FAIM2 knockout mice following experimental retinal detachment." (PMID 39311341, 2024). "Our data also show that the photoreceptor intrinsically neuroprotective protein FAIM2 is induced and interacts with α-crystallins following retinal detachment." (PMID 39311341, 2024). "Our data show that FAIM2, an intrinsic neuroprotective protein in photoreceptors, interacts with αA and αB-crystallins following retinal detachment." (PMID 39311341, 2024). "To confirm the role of αA- and αB-crystallins in the regulation of neuroprotective factors, we immunoprecipitated FAIM2 and assessed the pull-down of αA- or αB-crystallin shortly after experimental retinal detachment." (PMID 39311341, 2024). "Our results demonstrate that retinal detachment increases Faim2 protein levels in vivo, and this finding is reproduced in vitro by exogenous activation of Fas signaling in 661W cells." (PMID 23029562, 2012). "We observed that levels of Faim2 started to increase within 4 h of retinal detachment and peaked by 24 h." (PMID 23029562, 2012). "In our microarray gene expression study of retinal detachment, we found that Faim2 was induced at 24 h after retina-RPE separation." (PMID 23029562, 2012). "This interaction may be important for stabilizing FAIM2 and increasing total protein levels in photoreceptors, facilitating their ability to resist apoptotic stress after retinal detachment." (PMID 39311341, 2024). "Thus, in the current study, we decided to assess the functional relationship between FAIM2 and αA-crystallin in photoreceptors after retinal detachment." (PMID 39311341, 2024). "When we treated 661W cells with Fas-AAb, Faim2 expression increased significantly, demonstrating that similar to our in vivo results in the experimental retinal detachment, direct activation of Fas receptor signaling in 661W photoreceptors leads to elevated Faim2 levels." (PMID 23029562, 2012). "We first analyzed Faim2 expression and MAPK signaling during photoreceptor apoptosis using our well-established in vivo model of experimental retinal detachment." (PMID 23029562, 2012). "We next determined whether the Faim2 increase seen in our in vivo system of experimental retinal detachment could be modeled using our in vitro assay of Fas-mediated photoreceptor apoptosis; the primary pathway leading to photoreceptor death during retinal detachment." (PMID 23029562, 2012).
bone metastasis (1 paper, 2021). Transfer of a neoplasm from its primary site to bones. "FAIM2 expression was positively associated with the tumor stage, lymph node metastasis, bone metastasis, and poor prognosis of NSCLC." (PMID 34568020, 2021). "Samples of normal lung tissue and NSCLC tissue (with or without bone metastasis) were collected and analyzed for FAIM2 expression." (PMID 34568020, 2021).
carcinoid tumor (1 paper, 2016). A slow growing neuroendocrine tumor, composed of uniform, round, or polygonal cells having monotonous, centrally located nuclei and small nucleoli, infrequent mitoses, and no necrosis. "Therefore, the differential expression of FAIM2 between typical and atypical carcinoid tumors is a useful and meaningful diagnostic marker." (PMID 27677402, 2016). "As atypical carcinoid has been shown to have worse clinical outcomes than typical carcinoid, our data suggests that FAIM2 may be a useful diagnostic marker for atypical carcinoid." (PMID 27677402, 2016). "In this study, we observed that FAIM2 mRNA levels in atypical carcinoids are significantly overexpressed compared to typical carcinoids (p = 0.007)." (PMID 27677402, 2016). "We have demonstrated that FAIM2 can distinguish between atypical and typical carcinoids and between SCLC and NSCLC tumors as a selective and specific diagnostic marker." (PMID 27677402, 2016). "Interestingly, FAIM2 expression in atypical carcinoids was significantly higher than in typical carcinoids (p = 0.007)." (PMID 27677402, 2016). "In addition, FAIM2 expression is significantly higher in atypical carcinoid than typical carcinoid." (PMID 27677402, 2016).
Cerebral ischemia (1 paper, 2014). Restriction of arterial blood supply to the brain associated with insufficient oxygenation to support the metabolic requirements of the tissue. "Although, in animal models, it has been shown that Faim2 is a novel neuroprotective molecule in the context of cerebral ischemia, there are no studies on humans that have analyzed the association between FAIM2 polymorphisms and cerebrovascular disease risk." (PMID 24393375, 2014).
colon adenocarcinoma (1 paper, 2022). "Notably, FAIM2 expression is inversely correlated with most immune checkpoint genes in colon adenocarcinoma (COAD), GBM and LGG." (PMID 36185230, 2022).
diffuse large B-cell lymphoma (1 paper, 2022). "Overall survival analysis revealed that high expressed FAIM2 is linked to better prognosis for cancers including BRCA, lymphoid neoplasm diffuse large B-cell lymphoma (DLBC), HNSC, LGG, and LUAD of TCGA datasets, while there is an opposite trend in BLCA, GBM, and KIRC." (PMID 36185230, 2022).
epilepsy (1 paper, 2024). A brain disorder characterized by episodes of abnormally increased neuronal discharge resulting in transient episodes of sensory or motor neurological dysfunction, or psychic dysfunction. "Five feature genes, namely CD38, FAIM2, IL1B, PAWR, and S100A8, were identified as diagnostic biomarkers for epilepsy subtyping, forming the basis for constructing a disease classification model." (PMID 38384278, 2024). "Combining the results of both algorithms, we identified five feature genes (CD38, FAIM2, IL1B, PAWR, S100A8) as diagnostic biomarkers for epilepsy grouping." (PMID 38384278, 2024). "The results showed that the gene FAIM2 played an important functional role and might be a crucial gene in the context of epilepsy." (PMID 38384278, 2024).
glioblastoma (1 paper, 2020). The most malignant astrocytic tumor (WHO grade IV). "We analyzed the FAIM2, DLGAP2, ATP1B1 and RALYL alterations using the cBioPortal online tool for Glioblastoma Multiforme (TCGA, Firehose Legacy)." (PMID 33323543, 2020).
Hepatic steatosis (1 paper, 2025). Steatosis is a term used to denote lipid accumulation within hepatocytes. "High-fat and high-cholesterol diet-induced hepatic steatosis, inflammation and fibrosis are aggravated in Faim2-knockout mice and alleviated in mice with AAV8-mediated FAIM2 overexpression." (PMID 41057543, 2025). "In addition, higher serum lipid levels, such as TG and TC levels, as well as more severe hepatic steatosis in Faim2-KO mice than in WT mice fed a HFHC diet were also observed." (PMID 41057543, 2025). "Importantly, FAIM2 overexpression pronouncedly alleviated hepatic steatosis, inflammation and fibrosis in the AAV8-Faim2 mice." (PMID 41057543, 2025).
lung carcinoids (1 paper, 2016). "We extracted RNA from 24 lung carcinoids (16 typical and 8 atypical) and their matched normal tissues and performed qRT-PCR for FAIM2 expression." (PMID 27677402, 2016).
paraganglioma (1 paper, 2022). A benign or malignant neoplasm arising from paraganglia located along the sympathetic or parasympathetic nerves. "On the contrary, the expression levels of FAIM2 are higher in liver hepatocellular carcinoma (LIHC) and pheochromocytoma and paraganglioma (PCPG) than in normal tissues." (PMID 36185230, 2022).
periodontitis (1 paper, 2024). An acute or chronic inflammatory process that affects the tissues that surround and support the teeth. "Other proteins seen in this network are FAIM2 -Fas apoptotic inhibitory molecule 2,otherwise called as NMP35 protein or LFG (lifeguard) enables calcium-channel activity, involved in regulation of neuron apoptic process.Annexin (ANXA1) a cytoskeletal protein involved in progression of Periodontitis." (PMID 40230956, 2024).
rhabdomyosarcoma (1 paper, 2022). A rare aggressive malignant mesenchymal neoplasm arising from skeletal muscle. "In all 3 cell lines, immortalized myoblasts, rhabdomyosarcoma cells, and 293 T epithelial cells, we observed a DUX4 dose-responsive reduction in FAIM2 protein, shortly after induction." (PMID 35468884, 2022).
sarcopenia (1 paper, 2021). Progressive decline in muscle mass due to aging which results in decreased functional capacity of muscles. "While the effect of GALNT7 and FAIM2 in tumor progression is known (the former favoring and the latter impairing tumor growth), their function in the context of skeletal muscle, exercise and contrast to sarcopenia is less obvious." (PMID 33546468, 2021).
skin cutaneous melanoma (1 paper, 2022). "In various tumors including BLCA, HNSC, KIRP, LIHC, LUSC, PRAD, skin cutaneous melanoma (SKCM), THCA, and uveal melanoma (UVM), FAIM2 expression was positively correlated with ImmuneScore and StromalScore." (PMID 36185230, 2022).
tumor (16 papers, 2015 to 2025). "FAIM2 plays an essential role in the tumor microenvironment and is closely associated with immune Infiltration in various tumors." (PMID 36185230, 2022). "Our results revealed that FAIM2 is downregulated in most tumors, influences the prognosis of various kinds of cancer patients, and is associated with various tumor grades." (PMID 36185230, 2022). "In addition, we further explored the potential association between FAIM2 expression and tumor infiltrating immune cells (TIICs), immune subtypes, molecular subtypes, and promising immune biomarkers in the tumor microenvironment (TME)." (PMID 36185230, 2022). "FAIM2 expression is associated with tumor immune infiltration and may be able to modulate tumor prognosis by interacting with tumor immune cell infiltration." (PMID 36185230, 2022). "FAIM2 also exhibited a diagnostic value in tumor progression." (PMID 34568020, 2021). "Comparative analysis of our data with TCGA and CPTAC cohorts showed that both NPY and FAIM2 hyper-methylation and down-regulations can be novel epigenetically regulated genes in the Indian patient population, statistically significantly associated with poor survival and advanced tumour stages." (PMID 36329447, 2022). "FAIM2 expression and clinical stages in tumor samples and para-cancerous samples were analyzed by TIMER2 database, GEPIA database, and the TISIDB database." (PMID 36185230, 2022). "In the current study, FAIM2 acted as a tumor promoter in three tumor types and a tumor suppressor in one tumor type." (PMID 36185230, 2022). "Using IHC method, in separate validation cohort 4, we further showed that the protein expressions of both Faim2 and Npy were lower in tumour tissues compared to adjacent normal counterpart sections." (PMID 36329447, 2022). "Taken together, our first pan-cancer analysis of revealed the critical involvement of FAIM2 in tumorigenesis, clinical prognosis, and tumor immune infiltration." (PMID 36185230, 2022). "In the future, prospective research concentrating on FAIM2 expression and tumor immune infiltration would be useful in providing a conclusive answer, thereby developing immune-based anticancer therapies." (PMID 36185230, 2022). "In our RNA-seq datasets, FAIM2 transcription was significantly higher in tumor cells than in bone marrow-derived MNCs." (PMID 34503120, 2021). "First, the levels of FAIM2 expression in NSCLC tumor tissues and adjacent normal tissues, as well as in NSCLC tissues with or without bone metastasis were examined by Western blotting." (PMID 34568020, 2021). "We found vast tumor cell diversity and identified a marker protein, FAIM2, which can help to identify a broader range of tumor cell variants." (PMID 34503120, 2021). "The anti-tumor effect is believed to be mediated via controlling the level of Fas apoptotic inhibitory molecule 2 (FAIM2)." (PMID 34359780, 2021). "FAIM2 is an anti-apoptotic molecule that promotes tumor cell growth through Fas-mediated mechanisms." (PMID 32328342, 2020). "In NSCLC, it was reported that lncRNA-SNHG7 functioned as a molecular sponge and sequestered miR-193b from FAIM2, thereby impaired miR-193b/FAIM2-induced tumor progression." (PMID 31720124, 2019). "A study revealed great diversity among disseminated NB tumor cells, and suggested that FAIM2 (Fas apoptotic inhibitory molecule 2) might be a complementary marker to capture metastatic tumor cells." (PMID 35884407, 2022). "Interestingly, cancer-associated fibroblasts were negatively correlated with FAIM2 expression only in LGG, GBM, and PCPG, the correlation of FAIM2 and CAFs in other tumor types still needs further investigation." (PMID 36185230, 2022). "FAIM2 was originally discovered to antagonize Fas-mediated cell death, and has been identified as a protective factor in a number of diseases as well as a factor promoting tumor growth and aggressiveness of various cancers." (PMID 35468884, 2022).